ASL (argininosuccinate lyase)
Description:
Catalyzes the reversible cleavage of L-argininosuccinate to fumarate and L-arginine, an intermediate step reaction in the urea cycle mostly providing for hepatic nitrogen detoxification into excretable urea as well as de novo L-arginine synthesis in nonhepatic tissues. Essential regulator of intracellular and extracellular L-arginine pools. As part of citrulline-nitric oxide cycle, forms tissue-specific multiprotein complexes with argininosuccinate synthase ASS1, transport protein SLC7A1 and nitric oxide synthase NOS1, NOS2 or NOS3, allowing for cell-autonomous L-arginine synthesis while channeling extracellular L-arginine to nitric oxide synthesis pathway.
Synonyms: ASAL; ASLD
Tractability: Small molecule: it has a binding pocket of medium quality. PROTAC: ubiquitination databases record sites on it; its protein half-life has been measured.
Gene: Protein-coding gene on chromosome 7 (66,075,800 to 66,094,697, forward strand). Ensembl gene ENSG00000126522.
Subcellular location (Human Protein Atlas): Cytosol
Pathways (Reactome):
Disease: ASL variants cause argininosuccinate aciduria
Metabolism: Urea cycle
Gene Ontology:
Molecular function: argininosuccinate lyase activity; identical protein binding; protein binding; catalytic activity
Biological process: arginine metabolic process; L-arginine biosynthetic process; positive regulation of nitric oxide biosynthetic process; urea cycle
Cellular component: extracellular exosome; cytoplasm; cytosol
Genetic constraint (gnomAD): Loss-of-function variants: 51 observed, 68.76 expected, observed/expected ratio (o/e) 0.74, 90% interval 0.59 to 0.94. The upper end of that interval is the gene's LOEUF score, 0.94, which puts it in group 3 of 6, group 1 being the genes least tolerant of losing a copy. Missense variants: 540 observed, 636.47 expected, observed/expected ratio (o/e) 0.85, 90% interval 0.79 to 0.91. Synonymous variants: 241 observed, 253.14 expected, observed/expected ratio (o/e) 0.95, 90% interval 0.86 to 1.06.
Gene-disease validity (ClinGen):
ClinGen rates the evidence that ASL causes each of these diseases.
argininosuccinic aciduria (autosomal recessive): Definitive.
Homologues: Orthologues: chimpanzee ASL (99% identical), pig ASL (95% identical), mouse Asl (94% identical), guinea pig ASL (92% identical), macaque ASL (91% identical), rat Asl (89% identical), rabbit ASL (88% identical), dog ASL (80% identical), zebrafish asl (70% identical), tropical clawed frog asl (60% identical), Drosophila melanogaster Argl (52% identical). Paralogues in human: ADSL (22% identical), FH (20% identical).
Diseases named in the same sentence as ASL in open-access papers:
ASL is named in the same sentence as 53 diseases in open-access papers, as found by Europe PMC text mining. Sharing a sentence is not in itself a finding about the gene and the disease. The quoted sentences say what the papers report.
argininosuccinic aciduria (14 papers, 2010 to 2025). "The diagnosis of argininosuccinic aciduria was confirmed via molecular genetic testing (heterozygous genotype, with mutations c.1129C > G and c.1322G > A in the ASL gene)." (PMID 40310096, 2025). "We then examined various ASL sequence variants that are known to cause argininosuccinic aciduria, with residual enzyme activity ranging from 0% to 6.09% 12,52." (PMID 40307426, 2025). "ASL deficiency (ASLD) is caused by mutations in the ASL gene, located on human chromosome 7, locus 7q11.21." (PMID 37371829, 2023). "Argininosuccinic aciduria (ASA) is a metabolic disorder caused by a deficiency in argininosuccinate lyase (ASL), which cleaves argininosuccinic acid to arginine and fumarate in the urea cycle." (PMID 37371829, 2023). "This ASL-deficient mouse model recapitulates the human phenotype of inherited ASL deficiency also referred to as argininosuccinic aciduria." (PMID 31718089, 2019). "Pathogenic variants in the argininosuccinate lyase (ASL) gene have been shown to cause argininosuccinate lyase deficiency (ASLD); therefore, sequencing analysis offers advantages for prenatal testing and counseling in families afflicted with this condition." (PMID 31183366, 2019). "Argininosuccinate lyase (ASL) gene mutations account for argininosuccinic aciduria (ASA)." (PMID 31156699, 2019). "Biallelic pathogenic variants in ASL cause ASL deficiency (ASLD; argininosuccinic aciduria; OMIM #207900), the second most common urea cycle disorder (UCD), which has an estimated incidence of 1 in 218,750 births." (PMID 37490345, 2023). "Argininosuccinic aciduria (ASAuria; OMIM 207900) or argininosuccinate lyase (ASL; EC 4.3.2.1) deficiency is an autosomal recessive inborn error of the urea cycle." (PMID 20298553, 2010).
urea cycle disorder (10 papers, 2012 to 2025). A genetic inborn error of metabolism characterized by the deficiency of one of the enzymes necessary for the urea cycle. "We reported the variants of CPS1, ASS, ASL and OTC detected in the patients with urea cycle disorders through a nation-wide survey in Japan." (PMID 36303552, 2022). "Sequencing analysis with a panel including causative genes for urea cycle disorders (ARG1, ASL, ASS1, CPS1, NAGS, OTC, and SLC25A15) revealed a homozygous variant in intron 15 of ASL (NC_000007:c.1144-9 G > A) in the patient." (PMID 36097158, 2022). "Six of the 61 patients with small molecule disorders had a urea cycle disorder (CPS1, OTC, and ASL deficiencies)." (PMID 36101823, 2022). "Argininosuccinate lyase deficiency (ASLD, MIM #207900) is an inherited urea cycle disorder." (PMID 34765397, 2021). "Four genes (OTC, ASL, CPS1, and ASS1) were responsible for urea cycle disorders, accounting for 14.6% (13/89)." (PMID 34733806, 2021). "ASL, argininosuccinate lyase; ASS, argininosuccinate synthase; CPS, carbamoyl phosphate synthase I; i.v., intravenous; OTC, ornithine transcarbamylase; UCD, urea cycle disorder." (PMID 32269302, 2020). "ASL, argininosuccinate lyase; ASS, argininosuccinate synthase; CPS, carbamoyl phosphate synthase I; NKRT, non-kidney replacement therapy; OTC, ornithine transcarbamylase; UCD, urea cycle disorder." (PMID 32269302, 2020).
Hyperammonemia (7 papers, 2017 to 2025). An increased concentration of ammonia in the blood. "Mutated ASL enzyme leads to a loss of hepatocyte homeostasis and results in hyperammonemia, encephalopathy, and respiratory alkalosis." (PMID 37371829, 2023). "For example, a late-onset ASL deficiency that led to hyperammonemia was triggered by influenza infection in an adolescent patient." (PMID 37371829, 2023). "Inherited ASL deficiency causes argininosuccinic aciduria (ASA), a rare disease with hyperammonemia and NO deficiency." (PMID 38044746, 2024). "ASS1 and argininosuccinate lyase (ASL) are both urea cycle enzymes and deficiency in ASS1 and ASL are genetic disorders that can lead to hyperammonemia in humans." (PMID 38233193, 2024).
glioma (5 papers, 2019 to 2024). A benign or malignant brain and spinal cord tumor that arises from glial cells (astrocytes, oligodendrocytes, ependymal cells). "ADT, by nutrient starvation or exposure to ADI-PEG20, induces adaptive transcriptional upregulation of ASS1 and ASL in glioma cells in vitro, thereby conferring resistance to ADI-PEG20 treatment." (PMID 35898872, 2022). "Previous studies have revealed that KLF7 can promote polyamine biosynthesis and glioma development by activating argininosuccinate lyase, and meanwhile, KLF7 can be modulated by Linc00669/miR-193a axis and it can advance non-small cell lung cancer, suggesting that KLF7 is an oncogene." (PMID 32677950, 2020). "Importantly, KLF7 can enhance glioma progression by transcriptionally activating argininosuccinate lyase." (PMID 32677950, 2020). "Moreover, a previous study reported that KLF7 transcriptionally activated argininosuccinate lyase, which resulted in polyamines production and the oncogenesis of glioma." (PMID 31552163, 2019). "Recent studies have shown that epigenetic changes in two genes involved in arginine biosynthesis in gliomas, namely CpG island methylation of ASS1 and ASL, lead to decreased protein expression." (PMID 35898872, 2022). "The elevated levels of other metabolic enzymes including argininosuccinate lyase (ASL), ARG2, and COX-2 in glioma cells led to augmented synthesis of Trp, arginine and PGE2, which induced the repression of CTLs as well." (PMID 34211978, 2021). "Furthermore, we found that six downregulated genes, including pLCE1, PRPS2, FH, ASL, DTYMK, and CTPS1 were significantly increased in high-grade glioma tissues (p < 0.001)." (PMID 38438374, 2024).
citrullinemia (3 papers, 2019 to 2025). Citrullinemia is an autosomal recessively inherited disorder of urea cycle metabolism and ammonia detoxification characterized by elevated concentrations of serum citrulline and ammonia. "Firstly, physicians have to wait for results of chromatography of amino acids (CAA) to rule out citrullinemia, arginase 1 or argininosuccinate lyase deficiency before citrulline supplementation can be initiated." (PMID 37480106, 2023). "By contrast, UCDs caused by cytosolic enzyme deficiencies are treated differently; citrulline is not recommended for individuals with argininosuccinate lyase deficiency and citrullinemia, and supplementation with arginine is not recommended for arginase 1 deficiency." (PMID 37480106, 2023).
colitis (3 papers, 2021 to 2023). Inflammation of the colon. "Accordingly, an upregulation of the expression of the argininosuccinate lyase (ASL), the only enzyme able to produce L-arginine, was correlated with improved epithelial integrity and alleviation of colitis." (PMID 36982235, 2023). "Using Argininosuccinate lyase (ASL) knockout mice induced with colitis, it was revealed that enterocytes-derived NO alleviated colitis by reducing macrophage infiltration and tissue damage." (PMID 34836037, 2021).
Hypertension (3 papers, 2021 to 2025). The presence of chronic increased pressure in the systemic arterial system. "Argininosuccinic acid (2545-fold) was cleaved by argininosuccinate lyase (ASL) into arginine and fumarate—the latter suppressing hypertension via KCNMB1 downregulation—while reducing glutathione (GSH) and elevating malondialdehyde (MDA) in brain tissues." (PMID 40941158, 2025). "Deficiency of ASL, a candidate for both CKD and MI, is a rare genetic disorder resulting in argininosuccinic aciduria, a defective urea cycle condition leading to the insufficient breakdown/removal of nitrogen from the body, and consequently the patients develop hypertension." (PMID 37123453, 2023).
Argininemia (2 papers, 2019 to 2025). Arginase deficiency is a rare autosomal recessive amino acid metabolism disorder characterized clinically by variable degrees of hyperammonemia, developing from about 3 years of age, and leading to progressive loss of developmental milestones and spasticity in the absence of treatment. "With the exception of Argininemia, Arg can be supplied to all patients with UCDs, while Cit should not be supplemented in Argininosuccinate Synthase 1 (ASS1) and Argininosuccinate Lyase (ASL) deficiencies." (PMID 40428324, 2025).
breast carcinoma (2 papers, 2024 to 2025). "Similar effects have been observed in breast cancer cells, where the artificially high arginine levels in DMEM F-12 result in the enzymatic reversal of argininosuccinate lyase (ASL), which canonically catalyzes the conversion of argininosuccinate to arginine and fumarate." (PMID 40603611, 2024).
citrin deficiency (2 papers, 2014 to 2025). "Enzyme defects include deficiency of carbamylphosphate synthase, N-acetylglutamate synthase, ornithine transcarbamylase, argininosuccinate lyase and arginase, transporter defects are citrin deficiency and HHH-syndrome." (PMID 40285952, 2025). "Among these, argininosuccinate lyase (ASL) and citrin deficiency are usually associated with severe liver disease." (PMID 25132997, 2014).
Ornithine transcarbamylase deficiency (2 papers, 2018 to 2022). "The affected patients most frequently suffered from ornithine transcarbamylase deficiency (OTC-D) (female n = 12, male n = 12), followed by argininosuccinate synthetase deficiency (ASS-D, n = 13) and argininosuccinate lyase deficiency (ASL-D, n = 8)." (PMID 35626889, 2022).
brain tumours (1 paper, 2021). "Interestingly, expression of ASL, GATM, ODC, SLC25A13 and SLC25A15 is increased in tumours compared to normal brain tissue, indicating that the arginine biosynthesis pathway could be highly active in human brain tumours." (PMID 33809510, 2021).
carbohydrate metabolic disorder (1 paper, 2024). "ASL, AGL and GBE1 are among 135 genes revealed to be co-expressed in carbohydrate metabolic disorder." (PMID 38592052, 2024).
cervical cancer (1 paper, 2020). A primary or metastatic malignant neoplasm involving the cervix. "Our studies demonstrated that BCA-M significantly inhibited the growth of human cervical cancer cells in vitro regardless of argininosuccinate synthetase (ASS) and argininosuccinate lyase (ASL) expression." (PMID 33050217, 2020).
colorectal tumors (1 paper, 2023). "Arginine succinate synthetase (ASS) and argininosuccinate lyase (ASL), enzymes that catalyze arginine synthesis from citrulline, have been identified as upregulated targets in primary human colorectal tumors." (PMID 37762044, 2023).
developmental arrest (1 paper, 2014). "It seems as if the expression of CPS1, OTC, ASL, NAGS and GLUD1 in dogs with CPSS has come to a developmental arrest which prevented them to normalize after closure of the shunt." (PMID 24945279, 2014).
epithelial ovarian tumors (1 paper, 2023). "Argininosuccinate synthase (ASS) and lyase (ASL) are responsible for Arg synthesis, and accordingly, increased ASS mRNA and protein expression has been found in epithelial ovarian tumors, while ASL overexpression has been reported in other cancer types." (PMID 36765849, 2023).
fibrosis (1 paper, 2021). the formation of excess fibrous connective tissue in an organ or tissue in a reparative or reactive process. "We found the expression of OTC, CPS1, ASS1, and ASL was highly upregulated in BLM-induced fibrosis, and these enzymes were also downregulated after treatment with TL." (PMID 33995084, 2021).
Gaucher disease (1 paper, 2022). Gaucher disease (GD) is a lysosomal storage disorder encompassing three main forms (types 1, 2 and 3), a fetal form and a variant with cardiac involvement (Gaucher disease - ophthalmoplegia - cardiovascular calcification or Gaucher-like disease).
hepatocellular carcinoma (1 paper, 2021). A malignant tumor that arises from hepatocytes. "A possible explanation is a secondary function of ASL, as it has been shown to influence cyclin A2 levels by direct binding in hepatocellular carcinoma, independent of its enzymatic activity within the ASS1-ASL node that also promoted anchorage-independent growth." (PMID 34535676, 2021).
hypothyroidism (1 paper, 2014). Abnormally low levels of thyroid hormone. "Hypothyroidism impaired body weight gain and decreased circulating levels of IGF-I and biological markers of GH-STAT5b signaling activity in the liver (i.e., mRNA levels of IGF-I, ASL, SOCS2, CIS, and CYP2C11)." (PMID 24816529, 2014).
iron-deficient anemia (1 paper, 2020). "A previous study reported that the upregulation of argininosuccinate lyase during iron-deficient anemia may apply nitrogen atoms for the urea cycle in a DNA microarray study." (PMID 32764239, 2020).
kidney failure (1 paper, 2023). An acute or chronic condition that is characterized by the inability of the kidneys to adequately filter the blood. "In addition, the relative presence of arginine compared with citrulline (Arg/Cit) was progressively lower with the advancement in kidney failure, suggesting a lower activity of argininosuccinate synthase and/or argininosuccinate lyase." (PMID 36982658, 2023).
necrotizing enterocolitis (1 paper, 2015). Necrotizing enterocolitis (NEC) is a devastating disease that affects mostly the intestine of premature infants. "However, recently ASL deficiency was studied in necrotizing enterocolitis, for which a enterocyte-specific heterozygotic deletion of ASL mouse model was developed (Aslflox/flox; VillinCretg/+ or CKO)." (PMID 25699985, 2015).
neuroblastoma (1 paper, 2025). Neuroblastoma (NB) is the most common solid, extracranial childhood tumor. "While ASS1 expression did not correlate with BCT-100 IC50 in neuroblastoma cell lines, upregulation of ASS1/ASL/OTC was observed in some BCT-100 treated Th-MYCN tumors." (PMID 40813699, 2025).
osteosarcoma (1 paper, 2021). A usually aggressive malignant bone-forming mesenchymal neoplasm, predominantly affecting adolescents and young adults. "L-ARG availability can be regulated by the recycling of citruline through the argininosuccinate synthase and argininosuccinate lyase enzymes, but it is a pathway that needs further clarification in the osteosarcoma cell lines." (PMID 33562042, 2021). "There are indications that argininosuccinate synthase is involved in the metastatic process of osteosarcoma, but we still do not know if argininosuccinate lyase is expressed in these cells." (PMID 33562042, 2021).
Parkinson disease (1 paper, 2023). A progressive degenerative disorder of the central nervous system characterized by loss of dopamine producing neurons in the substantia nigra and the presence of Lewy bodies in the substantia nigra and locus coeruleus. "Although there is limited evidence in PDD, one study showed decreased arginine levels, but no detection of other urea-cycle intermediates, as well as increased mRNA expression of arginase and argininosuccinate lyase in a drosophila model of Parkinson’s disease." (PMID 37520429, 2023).
rectal carcinoma (1 paper, 2022). A malignant epithelial neoplasm that arises from the rectum and invades through the muscularis mucosa into the submucosa. "It is important to point out that Kaplan–Meier analysis showed that high expression of two enzymes, ornithine transcarbamoylase (OTC) and argininosuccinate lyase (ASL), was correlated with poor survival in rectal carcinoma patients." (PMID 35906392, 2022).
schizophrenia (1 paper, 2011). A major psychotic disorder characterized by abnormalities in the perception or expression of reality. "Furthermore, the ASL gene maps to chromosome 22q13.1-q13.2 in humans and these chromosomal loci have been repeatedly linked to schizophrenia." (PMID 21575198, 2011).
triple-negative breast carcinoma (1 paper, 2023). An invasive breast carcinoma which is negative for expression of estrogen receptor (ER), progesterone receptor (PR), and human epidermal growth factor receptor 2 (HER2). "Using an isotope tracing approach, Tardito’s group observed that in triple-negative breast cancer (TNBC) cell lines arginine at an ultrahigh concentration is converted into argininosuccinate by argininosuccinate lyase (ASL), i.e., via the reverse reaction." (PMID 36515528, 2023).